CD44 (CD44 molecule (IN blood group))
Diseases named in the same sentence as CD44 in open-access papers (continued):
Sharing a sentence is not in itself a finding about the gene and the disease.
cancer (continued). "Our previous studies found that some stem-like cell markers (i.e., CD44) could enhancing EMT and metastatic ability of cancer cells." (PMID 35449126, 2022). "CD44 has been identified as a surface marker of cancer stem cell (CSC), especially the CD44v subtype is widely used to isolate and enrich CSC in different types of cancers." (PMID 35936713, 2022). "The phenotype of CTC-AT showed that the majority of sub- populations were characterized by the high expression of markers as CD44, CD90, CD105 and CD7 as well as elevated ALDH activity, thus suggesting the presence of cancer stem-like cells in CTC-AT population." (PMID 35820816, 2022). "The resulting NPs had dual-targeting, CD44 (HA), and mitochondrial-targeting properties (TPP), which was confirmed by the results showing that cancer cells favorably uptake these NPs via CD44 receptor-mediated endocytosis and are largely accumulated in mitochondria." (PMID 36297526, 2022). "To study SCLC heterogeneity during cancer malignant progression and metastasis, we first performed immunohistochemistry (IHC) staining in RP tumors using NE marker NCAM and mesenchymal marker CD44." (PMID 35967587, 2022). "The expression of another cancer stemness marker—an adhesion receptor CD44—seemed to be upregulated too, but the effect was not statistically significant." (PMID 35327461, 2022). "As expected, overexpression EHD1 enhanced the CSCs properties of LUAD cells, as further indicated by the 3D spheroid cancer models, the holoclone assay, stem cell marker evaluation, flow cytometric analysis of CD133‐ and CD44‐positive cells, and limiting dilution assay." (PMID 35485206, 2022). "In a previous study, we found that MBZ alone had anticancer effects in RT-resistant TNBC by inducing apoptosis and cell cycle arrest, suppressing the expression of cancer stem cell markers (CD44 and OCT3/4), and inhibiting cancer progression-related ESM-1 proteins." (PMID 36555137, 2022). "Cancer cells in the recurrence displayed a phenotype of epithelial–mesenchymal transition (EMT), as evidenced by increased expression of mesenchymal proteins CD44 and vimentin." (PMID 35692807, 2022). "Notably, we found an increased signaling of MIF-(CD74+CD44) in T-ICC between malignant cells and TAMs or T cells, which has been well documented to promote cancer progression." (PMID 35558087, 2022). "In addition, cluster 4 and 1 expressed cancer stem cell-like cells (CSCLCs) gene markers CD24, CD44, and EPCAM, whereas cluster 0 and 2 expressed CD44 and NOTCH2, a gene marker denoted the activation of CSCLCs." (PMID 35733218, 2022). "In our study, five DEPs (CD44, Stat3, CAMK2D, CAMK2B and CAMK2G) were identified in the proteoglycans in cancer signaling pathway, which worked together to modulate functions of this pathway, such as cell migration and invasion, cell adhesion, cell growth and survival." (PMID 36678534, 2022). "CD44 is a key regulator of PD-L1 expression in TNBC, and it could indirectly promote cancer cell proliferation and immune evasion through mediated PD-L1 expression." (PMID 36059470, 2022). "Immunofluorescence staining for the M2 marker CD204 and the cancer stem cell (CSC) markers CD44 and CD133 was performed in paired HCC and adjacent noncancerous tissues and HCC tissues stratified by response of SOR treatment." (PMID 36411463, 2022). "This is consistent with reports that CD44+/CD24+ are generally non-tumorigenic, whereas CD44+/CD24-/low cells show cancer stem cell properties." (PMID 36009407, 2022). "As a result, we observed significant enrichment of KDM6B on promoter regions of SOX2 and CD44 but not on SOX9 in detached cancer cells." (PMID 35186918, 2022). "Although CD44 is reported to be shed from the cell surface by MT1-MMP, it still was exploited for the creation of HA–drug bioconjugate carriers for selective delivery of various drugs such as paclitaxel, doxorubicin, camptothecin or cisplatin to cancer cells." (PMID 36430705, 2022).
cancer (continued). "We then highlight how TGF-β modulation may be a potent method to target mesenchymal (CD44+/CD24−) and epithelial (ALDHhigh) cancer stem cell (CSC) populations in TNBC models." (PMID 35326728, 2022). "However, in the case of combined Selumetinib- and Trametinib-resistant cancers, FN1 and CD44 were down-regulated; TIMP1 and SNAI2 were down-regulated only in Selumetinib-resistant ones; while SPARC was down-regulated in the case of Trametinib-resistant cancer." (PMID 35534592, 2022). "In diverse cancer types, correlation analysis between CDCA4 and checkpoint gene expression indicated a high connection (P<0.05) with TNF-related immune genes including TNFRSF8, TNFRSF14, TNFRSF18, CD70, CD44, and CD276 (B7-H3)." (PMID 35251007, 2022). "This could allow measuring multiple subpopulations of EVs presenting markers more specific for cancer-related EVs (such as CD24, CD44, or CD340)." (PMID 34935096, 2022). "Cancer stem cell markers also include NANOG, ALDH1, SOX2, OCT4, LGR5, CD44, and CD133; therefore, stemness may be judged by the expression of these markers." (PMID 34725550, 2021). "CD44, ABCG2, Nanog, SOX2, and Oct4 were identified as important stem-cell transcription factors or markers involved in maintaining the CSC-like phenotypes in many kinds of cancer." (PMID 33596919, 2021). "In addition, it was also found that the CD105+ cancer cells showed increased expression of other MSCs markers (CD73 and CD90), while decreased expression was marked for CD44 and CD146." (PMID 34439332, 2021). "To quantify differences in frequency of putative cancer stem cell populations in both cell lines, we used flow cytometry to assess the enzymatic activity of aldehyde dehydrogenases (ALDH) and the expression level of the cell surface markers CD44 and CD24." (PMID 34367990, 2021). "PGCCs have the properties of cancer stem cells (CSCs) and can express CSC markers CD44 and CD133." (PMID 34336846, 2021). "Interestingly, the association of a specific CD44 variant with metastatic progression or treatment resistance might make it a good candidate for selective cancer targeting, since CD44 variant isoforms are not as abundantly expressed in the normal tissue as the standard CD4424." (PMID 34018387, 2021). "Adhesion molecules CD44, CD133, and CD90 were found as CSCs markers in many cancer types." (PMID 34638298, 2021). "For example, CD44 binds to hyaluronic acid or osteopontin to maintain a CSC phenotype and promote epithelial-to-mesenchymal transition (EMT), which is required for radiation or drug resistance as well as metastasis in cancer cells." (PMID 34163000, 2021). "The results revealed that angiogenesis, glycolysis, and EMT were the biological process most correlated with CD44 expression, while the TNFα signaling via NFκB, angiogenesis, IL6_JAK_STAT3 pathway, and EMT were correlated with TNFRSF12A in cancer cells across CRC, LC, and SCC." (PMID 34676217, 2021). "Likewise, LINC00346 functions as a sponge for miR-34a and promotes cancer cell proliferation, invasion, and metastasis in gastric cancer by protecting NOTCH1, AXL, and CD44 from miR-34a-mediated degradation." (PMID 33763422, 2021). "CD44, a non-kinase transmembrane glycoprotein, is a well-known marker of cancer stem cells (CSCs) and mediates intercellular adhesion, regulating epithelial to mesenchymal transition and cancer progression." (PMID 34064074, 2021). "A microarray from 96 patients diagnosed with pancreatic ductal adenocarcinoma showed CD44+CD133+ markers for CSCs and CD204+ for TAM, suggesting a possible connection between CSCs and TAMs in cancers, which also appears to be correlated with overall decreased disease-free survival." (PMID 33613850, 2021). "Moreover, we discuss recent findings highlighting TGF-β inhibition as a potent method to target mesenchymal (CD44+/CD24−) and epithelial (ALDHhigh) cancer stem cell (CSC) populations." (PMID 34680503, 2021).
cancer (continued). "Furthermore, the inhibition of other negative regulators of ferroptosis, such as CD44 or newly identified heat shock protein b-1 (HSPB1), also has great potential in this anti-cancer therapeutic strategy." (PMID 34831207, 2021). "Silencing SRI resulted in a decrease in the cancer stem cell markers CD133, CD44, and SOX2." (PMID 34163033, 2021). "CD44 is a multifunctional protein involved in cell adhesion, migration and drug resistance, with a critical role in cell signaling and cell-ECM interactions in cancer." (PMID 34071794, 2021). "Previous studies have indicated that CD13, CD44, and CD133 are markers for cancer stem cells." (PMID 34563053, 2021). "As we and others have shown that several cancer stem cell inhibitors target high CD44 cell population and that CD44 is expressed in NEPC, it is tempting to conclude that targeted inhibition of CD44 expressing cells could also prevent the progression of t-NEPC." (PMID 33572108, 2021). "Organoids were also positive for multifunctional stem cell marker and cell-adhesion glycoprotein CD44, however they did not exhibit expression of other cancer stem cell markers such as OCT4, NANOG, SOX2, or ALDH1." (PMID 33732646, 2021). "Dormant and therefore therapy-resistant, CSCs or tumor-initiating cells are often responsible for relapse and can be characterized by the expression of numerous biomarkers such as CD44, CD24, CD29, CD49f, ALDH, CD105, CD133, or CD166, depending on the cancer type." (PMID 33808542, 2021). "Moreover, the CMCAFs treatment induced the expression of EMT and cancer stemness markers in NOZ and GBC-SD cells, as revealed by reduced E-cadherin expression and increased vimentin, Sox2, CD44, Nanog and Oct4 expression." (PMID 33407730, 2021). "The MMP-mediated cleavage of the CD44 ectodomain allows the release of cancer cells bound to hyaluronan, promoting their migration through hyaluronan-containing extracellular matrix (ECM) and facilitating cancer cell dissemination." (PMID 33804427, 2021). "ITPR3 and CSC markers such as CD44, SOX2 and OCT4 were enriched in BCa stem cells, which indicated that ITPR3 might play a vital role in maintaining the cancer stemness phenotype." (PMID 33573671, 2021). "Therefore, curcumin is a versatile agent in suppressing CSC features in cancer and various molecular pathways such as Wnt, Sonic, STAT3 and NF-κB, among others, are affected to reduce CSC markers such as CD44, ALDH and CD133." (PMID 34769099, 2021). "LCN2 silencing also significantly reduced the percentage of cancer stem cell populations in LCN2‐silenced IBC cells relative to control, as shown by reductions in primary and secondary mammosphere formation efficiency and CD44+CD24− cell subpopulations." (PMID 34342930, 2021). "CD44 is a nonkinase transmembrane glycoprotein that is expressed in several cell types including cancer stem cells." (PMID 33543833, 2021). "Additionally, association analysis of CMTM6 mRNA levels with Wnt target genes (TCF4, LEF1, CD-44, MMP14, ENC1, ID2, PPARA, and JAG1) from the cancer genome atlas HNSCC cohort using GEPIA showed a positive correlation (r > 0.2)." (PMID 33434185, 2021). "In recent years, researchers found CD44 was a biomarker of PDAC cancer stem cells 36, and could reflect initiation and metastasis of PDAC, which made CD44 a potential biomarker to predict PDAC." (PMID 33531989, 2021). "Anti-CD44 and anti-CD63 antibodies were here used to capture cancer and generic EVs." (PMID 34855021, 2021). "Importantly, CD44 and CD133 are the most widely used markers in CSCs research and they are also therapeutic targets in cancers." (PMID 34769230, 2021). "HNK also suppressed the expression of additional cancer stem cell marker proteins LGR5 and CD44." (PMID 34206989, 2021). "Moreover, the expression levels of the cancer stemness markers, NANOG, CD44, and KLF4, were markedly higher in 3D spheroids than in 2D monolayers." (PMID 34948357, 2021).
cancer (continued). "CD44 and EGFR are surface receptors that manifest themselves as important bio-markers in cancer." (PMID 34959436, 2021). "Since CD44+CD24– stem cell-like TNBC phenotype and PD-L1 upregulation require STAT3 signaling, these studies support our findings that the STAT3-activating property of PARPi can promote cancer progression and immunosuppression." (PMID 34956861, 2021). "Notably, the mRNA level of SLC27A6 was positively correlated with cancer stem cell (CSC) markers, CD24 and CD44." (PMID 35047398, 2021). "Considering the importance of the CD44-HA and RHAMM-HA interactions in tumor cells, they might be promising therapeutic targets for cancer treatment." (PMID 33888679, 2021). "By examining the expression pattern of cancer stem cells markers (e.g., PROM1, CD44, and EPCAM), it is found that CD44 positive population may render drug resistance in HCC272." (PMID 34105295, 2021). "CD44 is a cell surface glycoprotein and, as a CSC marker, plays an important role in cell migration and adhesion, tumor invasion, prognosis, and metastasis of cancers." (PMID 33681421, 2021). "Interestingly, the CD44/CD24 ratio, which positively correlates with the malignance of cancer, was the highest in H1975." (PMID 34127680, 2021). "CD44 is a non-kinase transmembrane glycoprotein frequently overexpressed in cancers and cancer stem cells." (PMID 34887764, 2021). "These letter results support previous studies demonstrating that different cancer cells express different CD44 isoforms, as do non-cancer cells." (PMID 33891595, 2021). "The excessive LDs could upregulate CD24, CD44 expression and promote maintaining NPC CSC stemness, which could be a possible mechanism explaining why SLC27A6 overexpression promoted cancer metastasis." (PMID 35047398, 2021). "Also, overexpression of miR-509-3p decreased expression of SOX2, CD44, and CD133, and enhanced expression of Bax and caspase-3 while repressed Bcl-2 expression in cancer cells." (PMID 34715859, 2021). "HOXB9 and CSC markers were simultaneously overexpressed in human refractory PCa tissues, compared with low-grade PCa, para-carcinoma, and initial PCa tissues implying the involvement of HOXB9 signalling’s involvement in ALDH+CD44+CXCR4+CD24+-PCa cell-rendered castration resistance." (PMID 34247196, 2021). "Furthermore, there was a reduction in expression of cancer stem cell marker proteins DCLK1, CD44, CD133, Oct-4, and ABCG2." (PMID 32094348, 2020). "Therefore, HA–BrBP obtained in this way was deemed to be suitable for specific binding to the CD44 and RHAMM receptors that are overexpressed on cancer cells." (PMID 32938918, 2020). "Although this resemblance served the purpose of properly separating cancer cell types, mesenchymal cancer cells lack expression of important tRG genes such as AQP4, FAM107A, SOX9, and GLI3, and tRG lack the expression of mesenchymal genes such as CD44 and TIMP1." (PMID 32641768, 2020). "Considering the importance of CD44 splicing for cancer progression, among the different RNA binding proteins (RBP) with predicted binding motifs in CD44 v10 region, we decided to focus our attention on those proteins whose expression levels are frequently altered in different cancer types." (PMID 33143085, 2020). "The cancer stem cell markers, CD24 and CD44, were also monitored." (PMID 33233485, 2020). "Because CD44 is often used as a marker of cancer stem cells, findings are often correlative rather than functional." (PMID 32455980, 2020). "Reported cooperation between CD44 and STAT3 in different cancer models." (PMID 33335857, 2020). "Cancer cells were stained with cytokeratin 19 (CK19), CD44, and ALDH1A1." (PMID 32155897, 2020). "Finally, we will discuss CD44 and STAT3 involvement in cancer-driven metabolism switches and summarize currently available data on CD44 therapeutic targeting alone or in combination with STAT3, highlighting promising therapeutic opportunities for the future." (PMID 33335857, 2020).
cancer (continued). "Moreover, its hub genes (CD44, PLOD1 and PLOD2) were proven to possess pro-cancer abilities through MTT and Transwell invasion assays." (PMID 33287763, 2020). "Contact-free co-culturing turned out to be entirely ineffective suggesting that paracrine factors released from the fibroblasts at distance are unlikely to play a major role in the CD44 induction in cancer cells." (PMID 32685007, 2020). "CD44 and Nanog belong to several regulators of CSCs and are abnormally high in CSC and can be used as markers for CSC and it is known that their expression is increased by EGF signaling pathway in several cancers including HCC16,17." (PMID 32376896, 2020). "PROM1, LGALS1, CD44, FUT4 and HOXA10 were identified as hub genes, which were involved in focal adhesion, calcium-dependent phospholipid binding, connective tissue development and transcriptional misregulation in cancer." (PMID 32347296, 2020). "Several research found differential expression of CD44 on cancer stem cells against non-cancer stem cells in different solid tumors." (PMID 32280305, 2020). "Additionally, several direct intracellular interactions between CD44 and STAT3 have been reported across different cancer models." (PMID 33335857, 2020). "Mechanistically, CD44 formed homophilic interactions independent of HA on the cancer cell surface, which in turn triggered activation of a serine/threonine-protein kinase 2 (PAK2) and focal adhesion kinase (FAK) dependent signaling cascade." (PMID 32984308, 2020). "For the specific characterization by flow cytometry and confocal microscopy, different commercial antibodies against selected receptors were used, including the general tetraspanins CD9, CD63 and CD81, and cancer-related receptors (CD24, CD44, CD54, CD326 and CD340)." (PMID 32054015, 2020). "The binding of hyaluronic acid with CD44 results in the activation of epidermal growth factor receptor family kinases such as the MAPK and PI3/AkT that in turn promotes growth and proliferation in various cancers." (PMID 33489917, 2020). "NIR-PIT targeting CD44 selectively induces necrotic/immunogenic cell death, unlike the apoptotic cell death induced by most other cancer therapies." (PMID 32937841, 2020). "PDAC cells enriched with CD44, and/or CD24 and/or CD133 are highly tumorigenic-resistant to conventional anti-cancer therapy, and have been used as cancer stemness markers." (PMID 32457900, 2020). "Furthermore, there was an autocrine feedback loops among ESRP1, HAS2, CD44, and ZEB1 in the aberrant activation of EMT, which acted in the dynamics of EMT in cancer metastasis." (PMID 32211324, 2020). "This study demonstrated that the HH pathway might regulate CD44+/CD24− CSC populations and increase the cancer stemness and therapy resistance." (PMID 32560537, 2020). "UWG01CTC had no detectable EpCAM, mesenchymal (NCAD, Vimentin), or cancer stem cell marker (CD44, CD133, ALDH1)." (PMID 31953491, 2020). "Cancer cells that undergo an EMT acquire properties of CSC and show enhanced CD44 expression." (PMID 34841087, 2020). "In line with this, it has been demonstrated that nicotine plays a critical role in the development of tobacco-induced cancers by increasing the expression of various CSC markers NANOG, OCT4, CD44, and BMI-1 and regulating CSC properties and tumorigenic potential in HNSCC models in vitro and in vivo." (PMID 32635524, 2020). "Interestingly, CD47 expression correlates with both CD44 expression and EMT, suggesting CD47 as a promoter of cancer cell stemness, tumor spreading, and resistance to PD-1/PDL-1 inhibitors." (PMID 32962159, 2020). "CD44, a non-kinase transmembrane glycoprotein, is regard as a marker of cancer stem cell (CSC) and can regulate the properties of CSCs, including cellular plasticity, self-renewal, invasiveness and treatment resistance." (PMID 33287763, 2020).